CCL5 (C-C motif chemokine ligand 5)
Diseases named in the same sentence as CCL5 in open-access papers (continued):
Sharing a sentence is not in itself a finding about the gene and the disease.
infection (continued). "In addition to TNF-α, CXCL10 (one of the top five hub genes), and CCL5, two chemokines also found to be the hallmarks of the inflammation caused by LgyLRV1+ infection were also found to be present in the 8h_bisque4." (PMID 35992159, 2022). "Notably, infection of both male or female mice with M. circinelloides resulted in reduced levels of CCL5, a chemokine usually associated with recruitment with T-cells, eosinophils and basophils." (PMID 33919611, 2021). "Further, the increased susceptibility to encephalitic symptoms after infection with West Nile virus, of individuals harbouring mutatedCCR5, which encode the receptor for CCL5, is thought to be due to failure of trafficking of T cells into the brain (Glasset al., 2005) and reviewed in." (PMID 31069065, 2019). "Indeed, increased leukocyte recruitment to the brain of IFN-α/βR −/− mice was detected after 6 days of infection and was associated with elevated levels of inflammatory mediators, such as the chemokines CCL5 and CXCL1 and the cytokines IL-1β and TNF-α." (PMID 28442607, 2017). "However, our results demonstrated that the inflammatory chemokines in chickens, CCL4 and CCL5, were induced by cNK-2 in innate immune cells, suggesting a role of this peptide in association with inflammatory response-mediated infections." (PMID 28332637, 2017). "Having established that MC-deficiency curtails mCMV-induced serum levels of the T and NK/NKT cell-recruiting chemokine CCL5, we quantitated CD3ε+ T cells in absolute terms for comparing infiltration of the lungs on day 6 after intravenous infection of WT C57BL/6 mice and MC-deficient “sash” mutants." (PMID 24763809, 2014). "In mice, the levels of CCL5 increased quickly in the brain microvasculature after infection, helping the infected immune cells adhere to brain vessels." (PMID 41528135, 2026). "Several cytokines (TNF, IL-1β) and chemokines (CXCL10, CCL2, CCL5) were reduced in the brains of Rag1–/– animals at day 14 after infection, which were restored or exceeded WT levels mainly with Th1 adoptive transfer, whereas Th17 cells were less effective." (PMID 39989461, 2025). "The host innate immune and inflammatory responses to infection were assessed by measuring changes in mRNA expression of a chemokine, CCL5, and an interferon-stimulated gene (ISG) IFIT2, using cell lysates harvested at 24 hpi." (PMID 40295862, 2025). "This agrees with the finding that the upregulation of TNF-α and CCL5 in plasma correlates with pathology during subcutaneous infection of BALB/c mice with VEEV TrD." (PMID 39936916, 2025). "The data revealed that NK cell-mediated modulation of CCR5 expression on DCs, along with the production of chemokines CCL3 and CCL5 in the lungs, contributed to DCs recruitment to infection sites." (PMID 40332391, 2025). "Greater CCL5 activity was predicted in C57BL/6 mice at 20 days after infection, whereas predicted activity of the chemokines CCL6, CCL9, CCL3, and CCL4 was highest in C3HeB/FeJ mice by 20 days after infection." (PMID 40986319, 2025). "The results showed that most pro-inflammatory markers, such as granzyme, Lamp1, Ifng, Prf1, Ccl5, Emoes, and Id2 transcription, increased after infection." (PMID 41459157, 2025). "In lung tissue, IL1B, IL6, IL10, CXCL2, CCL3 and CCL5 levels also rose in both genotypes following infection, although these markers were significantly lower in TLR7 KO mice." (PMID 40442368, 2025). "CCL5 levels were lower in both groups at timepoint A as opposed to timepoints B and C indicating differing kinetics in the first days of iGAS infection." (PMID 38865072, 2025). "To address this, we analyzed the transcriptional expression of the cytokines Il-6, Tnf, and the chemokine Ccl5/Rantes throughout the course of infection in the brain." (PMID 41362627, 2025).
infection (continued). "Mast-cell-derived cytokines and chemokines facilitate the migration of dendritic cells (DCs; TNF-α and CCL20) and effector T cells (CXCL10/IP10 and CCL5/RANTES) to the infection site and draining lymph nodes." (PMID 40867663, 2025). "Functionally, these molecular alterations translated into a diminished secretion of key inflammation and infection mediators, such as interleukin-6 (IL-6) and C-C Motif chemokine ligand 5 (CCL5) upon TNF-a stimulation." (PMID 41050669, 2025). "In immune cells at the site of infection, the expression of proinflammatory cytokines and the chemokine CCL5 increases, key in the development of chronic gastric inflammation and the onset of GC." (PMID 38455038, 2024). "More importantly, the activation of CCR5 by CCL5 plays a significant role in prolonging macrophage survival and controlling infection." (PMID 39061526, 2024). "CCL5 is a chemokine that is involved in the recruitment of immune cells to sites of infection or inflammation." (PMID 39028255, 2024). "CCL5 is an inflammatory chemokine that recruits leukocytes to the site of infection and can also be a potent leukocyte activator." (PMID 38695564, 2024). "Compared to “transient” CD8 T cells, the “durable” CD8 T cells upregulated the expression of chemokines such as CCL4 and CCL5, which attract immune cells to the site of infection, as well as cytotoxic protein marker NKG7." (PMID 38561339, 2024). "We want to highlight that CCL5′s role is essential for an effective immune response; defects in CCL5 expression lead to failure in infection control." (PMID 39590591, 2024). "Adding 25–100 μL (0.5–2 MOI) RV16 significantly induced CCL5 protein production in a virus dose- and infection time-dependent manner (p < 0.01)." (PMID 39598462, 2024). "Infection-induced upregulation of CCL5, IL-6, and IL-8 and increased activation of co-cultured endothelial cells, confirming data collected from cell lines and cord blood-derived mast cells." (PMID 38793609, 2024). "In the case of JEV, the infection of the pericytes can trigger the production of inflammatory molecules such as IL-6, RANTES (also known as CCL5) and PGE2." (PMID 39063134, 2024). "The inflammatory cytokines TNFα, IL-4, IL-6, IL-13, IL-10, IL-12 (P40), and IL-12 (P70) along with chemokines including CCL2, CCL3, and CCL5, were significantly elevated in the plasma of c-Flip+/–mice on day 2 post-infection compared that of WT mice." (PMID 39038037, 2024). "We previously showed that infection with RSV wt increased the expression of CCL5 and TNF-α proteins, and that this increase was less with mutants lacking either or both NS proteins." (PMID 38932114, 2024). "Conversely, control mice exhibit greater expression of Ccl5, Mmp8, Sfrp2, Tmem119, and Tnn after 14 days of infection." (PMID 37845223, 2023). "Similar to the response to WT STm infection, ΔprgH STm infected 2D enteroids regulated CCL5 and DTX2 at 4 hpi and genes involved in the regulation of antigen presentation (CD83), and inhibition of NFκB activation (NFAIP2)." (PMID 37854334, 2023). "Utilizing antibody immunofluorescence, we detected increased CCL5 expression in infected versus uninfected brains, with the mean volume of CCL5 to be 0.10 μm3 in infection and 0.01 μm3 in uninfected brains, P = 0.0047." (PMID 37945689, 2023). "For instance, infection of human bronchial epithelial cells with HRV-C has been shown to induce a lower cytokine release of CCL5, MCP-1 and IL-8 compared to infection with RSV." (PMID 36810092, 2023). "Researchers reported that infection with the genotype II highly virulent isolate SY18 resulted in increased serum values of CCL5 (RANTES) early after infection (2–4 dpi), which remained elevated until the end of the experimental study (7–8 dpi)." (PMID 36680273, 2023).
infection (continued). "When comparing the Control−, Control+, and pooled SIDS groups, almost all cytokines, except CCL5, were massively increased in the Control+ group, supporting the concept that lungs of infants are able to mount robust inflammatory responses to infection." (PMID 35986144, 2023). "It has been also established that genetic variations in the HIV-1 coreceptors (such as SNPs in CCR5) and in their ligands (such as SNPs in RANTES/CCL5) alter factors, such as infection severity." (PMID 37766364, 2023). "Following activation, virus-specific effector CD8+ T cells expand and migrate to the site of infection in response to chemoattractants CCL5 and CXCL10." (PMID 37896776, 2023). "CCL5 was also upregulated at the mRNA level in MDMs after infection with opsonized bacilli, even though memory CD8+ T-cells have a large amount of preformed CCL5 mRNA in the cytoplasm and chemokine secretion was reported to be dependent only on translation." (PMID 37781389, 2023). "The C-C chemokine ligand 5 (CCL5) is a member of the chemokine family, and CCL5 has a chemotactic effect on immune cells and induces activation of immune cells to fight infection." (PMID 37876591, 2023). "Lower age, PCR CT, IL-6, IL-8, and IL-17A and higher IL-16, EGF, and CCL-5 appeared to provide the best univariate class separation for recurrent infection (versus recurrence-free survival and death)." (PMID 36975808, 2023). "The SNPs rs2107538 and rs2280789, related to the higher expression of the CCL5/RANTES gene, were significantly associated with resistance to infection in several populations." (PMID 37766364, 2023). "Elevated expression of cardiac VEGF, Ang-1 and Ang-2, and reduced production of TNF and CCL5 were observed in the Y strain infection compared to the infection with the Colombian strain." (PMID 37998013, 2023). "A study in mice showed that infection with Aggregatibacter (Actinobacilus) actinomycetemcomitans increases CCL5 production in the gingiva." (PMID 38139161, 2023). "Filaggrin, HIF-1α, VEGF, RANTES/CCL5, IL-17A, IL-1β, MIP-1α and MIP-1β/CCL5 levels were higher during and after infection." (PMID 36482106, 2022). "This antigen-specific antibody-mediated infection was selectively coupled to chemokine ligand 5 (CCL5), interleukin 1β (IL-1β), and C-X-C motif chemokine ligand 10 (CXCL10) secretion and a reduction in granzyme B (GrB) release." (PMID 35862953, 2022). "Under the stimulus of the 501Y.V2/B.1.35 strain infection, the expression of IL-6, IL-8, IP-10, CCL-5, MIP-1α significantly increased after infection for 48 h compared with NC group (P < 0.001 or P < 0.01)." (PMID 35365215, 2022). "Monocytes and macrophage are mononuclear phagocytic leukocytes which are recruited to sites of infection by chemokines such as Chemokine (C-C Motif) ligand 5 (CCL5) and Monocyte Chemoattractant Protein-1 (MCP-1)." (PMID 36290196, 2022). "Ccr5, Ccl2, Ccl5, and Ccl7 were among the most significantly upregulated chemokine genes in SC samples at 1 wk post-infection." (PMID 36490282, 2022). "NEAT1-2, the longer transcript of NEAT1, is mainly located in the nucleus and has been reported to facilitate IL-8 and CCL5 production by sequestering SFPQ in paraspeckles after infection with various viruses." (PMID 35495674, 2022). "And the secretion of CCL5 was detected at 4 hours post-infection (h p.i.)at the early time of viral replication cycle and retained for at least 96 hours in the T7011-infected cells." (PMID 36353540, 2022). "The key driver of this retention seems to be CCL5, which is highly upregulated in vaginal tissue following immunisation and infection." (PMID 36211447, 2022). "Under the stimulus of the G/478 K.V1/ B.1.617.2 strain infection, the mRNA expression of IL-6, IP-10, CCL-5 and IL-1α significantly was increased after infection for 48 h compared with NC group (P < 0.001)." (PMID 35365215, 2022).
infection (continued). "CCL5, also known as RANTES, belongs to the family of chemotactic chemokines that promotes leukocyte trafficking to the site of infection and stimulate cytokine production." (PMID 36579331, 2022). "By contrast, the Ifih1−/−Sting1gt/gt AECII failed to induce Ifnb1, Ccl4, and Ccl5 gene expression and to produce IFN-β, CCL4 and CCL5 upon VACV∆C7L infection." (PMID 35351885, 2022). "Changes in expression levels of three different transcripts regulated during infection by L. donovani amastigotes (Ccl5), promastigotes (Cd274) or both (Hmox1) was confirmed by RT-qPCR experiments." (PMID 35430587, 2022). "This confirmed a significant increase in Il1b at 24 h following infection, with minimal induction of Il23a evident, as well as higher levels of monocyte and T cell chemoattractants Ccl4 and Ccl5." (PMID 35845169, 2022). "With the exception of CCL5, the inflammatory responses in the high dose group were usually higher 4 weeks post infection and then they declined by 7 weeks post infection." (PMID 36051240, 2022). "denticola infections decreased IL-6, IL-1β, and CCL5/RANTES compared to single species infections with each of the bacterium in macrophage/epithelial cell co-culture model." (PMID 35203495, 2022). "During Mtb infection, CCL5 regulates and activates the recruitment of macrophages, NK cells and T-cells to the site of infection to limit bacterial growth by establishing granulomas." (PMID 34516566, 2021). "The genes Mx2, Irf7, Ddx58 and Stat1gene transcripts were found up-regulated early in the infection (2 and 4 dpi), whereas Ccl5 was up-regulated only at 4 dpi." (PMID 33941622, 2021). "CCL5 levels were low in cultures from naïve cells and enhanced in ~50% of ECM susceptible WT mice following PbA infection." (PMID 34659202, 2021). "The host cells (EA.hy926) responded to the infection with an increased gene expression of CCL5, ICAM-1, IL-6, and CXCL10." (PMID 34490828, 2021). "There was an increase in the CCL5+ CD8+ T cell count (p=0.002) in Ifnar1-/- mice upon PbA-infection." (PMID 34659202, 2021). "There was a robust correlation between SARS-CoV-2 transcripts and the IFN-γ-induced chemokine Cxcl-10 (IP-10) and to a lesser extent Csf1, Ccrl2, and Ccl5, which are all involved in the recruitment of immune cells to the site of infection." (PMID 34319784, 2021). "VLV had a broader impact on gene expression in DCs after infection, upregulating genes related to inflammation (such as Ccl5, Ccl4, and IL12b), but also downregulating other genes." (PMID 34811393, 2021). "Pneumocystis infection appears to be associated with dysfunction of the IL-23/IL-17 axis, with higher lung fungal burdens and reduced production of IL-17 and chemokines CXCL10 (IP-10), CCL3, CCL4, and CCL5, all crucial for infection resolution." (PMID 34829225, 2021). "These signaling pathways showed that, after LPS infection, several DEGs were mainly related to immune function, such as up-regulated expression of CCL5, IL8, NFKBIA, TRAF3, and TNFAIP3, and down-regulated expression of MEF2C, MAP2K6, TLR1, TLR2, and IRF5." (PMID 34067819, 2021). "In response to H1N1 or H3N2, there was a marked elevation of Ccl3, Ccl4, Ccl5, and Cxcl10 in young lung at day 3 post infection." (PMID 34829979, 2021). "Both, eosinophil-depleted and isotype treated Ifnar1-/- mice had higher levels of CCL5 in the spleens during PbA infection compared to the infected WT controls." (PMID 34659202, 2021). "CCL5, also known as RANTES, is important for the recruitment and development of Th1 cells, which are responsible for the control of the infection." (PMID 34832536, 2021). "Genes encoding interferons (Ifnb, Ifnl2 and Ifnl3), chemokines (Ccl7, Ccl5, and Cxcl10), and ISGs (Ifit1, Ifit2, Ifit3b, Oas3, Ifi44, Rsad2, and Isg15, among others) were prominently represented among those induced by infection in Ifnar1-/- mice." (PMID 34591933, 2021).
infection (continued). "Upon PbA-infection the proportion of CCL5+ monocytes vanished, so that CD8+ T cells (17.8%), CD4+ T cells (16.8%) and eosinophils (16.7%), together with M2-like macrophages (9.2%) were the main CCL5 producers in spleens of PbA-infected Ifnar1-/- mice." (PMID 34659202, 2021). "We noted that many genes were upregulated and preserved after infection, including Nkg7, Ccl5, Ifng, and Ccl4, which reinforces that MAIT cells had acquired an altered cellular state." (PMID 34272362, 2021). "CCL5 expression most notably was completely abrogated as the infection transitioned into a quasi-dormant state." (PMID 34805001, 2021). "As for pro-inflammatory cytokines and chemokines, we observed that the transcripts of CCL5 (RANTES) increased significantly after infection whereas moderate increases of IL-18, IP-10 and TNF-α transcripts were detected in UT-SCC-60A cells." (PMID 33481814, 2021). "To allow statistical analysis of data, we compared the concentrations of IFN-γ and CCL5 in poly(I:C)-primed surviving animals (n = 9) versus vehicle-administered animals which succumbed to infection (n = 8)." (PMID 31952519, 2020). "Our results show that incubation of HRV with LL-37 alters the virus-mediated gene expression of IL-8, IL-6, and CCL5 mRNA in response to infection." (PMID 32117246, 2020). "In agreement with the in vivo results, the production levels of Ifnb, Isg15, and Ccl5 were much higher in the carvedilol-treated WT peritoneal macrophages, whereas the virus titers were lower after the infection." (PMID 33243993, 2020). "The levels of IL-2, IL-17 and CCL5 at 24 h after infection were regulated in a sex-dependent manner." (PMID 32373108, 2020). "We analyzed the mRNA expressions of selected inflammatory genes and observed a significantly higher expression of CCL5 after infection in WT neonatal mice compared to CRAMP−/− mice." (PMID 33113928, 2020). "After infection with the pathogenic fungi, they found that the production of IL-1β, IL-6, IL-8, IL-12, TNF-α, CCL2, and CCL5 was significantly increased after the addition of moDCs." (PMID 32957440, 2020). "Expression of chemokines involved in immune cell recruitment to tissue sites of infection, CCL5, CXCL10, CXCL9, and IL-15, were significantly lower in lung tissues of HTNV-infected Ifnar1-/- animals compared to WT controls." (PMID 32330200, 2020). "We found that both MLE-12 cells and polarized mouse tracheal epithelial cells (mTECs) were susceptible to infection with Influenza A and released proinflammatory cytokines, including CCL2, CCL5, CXCL1, and CXCL10, in response to replicating virus." (PMID 33374950, 2020). "Transcripts of Ifnb (B) or ISGs (Cxcl10, Isg20, Ccl5, Isg15) (C) were determined at 6 hr after infection." (PMID 32886065, 2020). "The only poly(I:C)-treated animal which succumbed to infection had a CCL5 concentration in the spleen of 1522 pg/mL." (PMID 31952519, 2020). "In fact, cultured human bronchial epithelial cells produced significant amounts of IL-6, IL-8, and CCL5 upon infection with A/Shisen/2/93 (H3N2) virus detectable from 24 h after infection." (PMID 33062077, 2020). "Transcripts of Ifnb (A) or ISGs (Cxcl10, Isg20, Ccl5, Isg15) (B) were determined 6 hr after infection." (PMID 32886065, 2020). "DC isolated early after infection of pigs with either of the two CSFV strains showed prominent upregulation of CCL5, CXCL9, CXCL10, CXCL11, and XCL1, as well as of the cytokines TNFSF13B, IL6, IL7, IL12B, IL15, IL27." (PMID 32733474, 2020). "CCL5 was found to be the highest upregulated chemokine gene in human neural cultures in response to infection with both CVS-11 and Z.Dog rabies infection compared to uninfected cultures." (PMID 32218146, 2020). "The analysis in this study revealed an increased inflammatory response, and the expression of CXCL1, CXCL12, CCL2 and CCL5 was significantly increased upon natural street RABV strain infection of dogs or humans compared to artificial mouse infection." (PMID 33081802, 2020).